PHF20L1 (PHD finger protein 20 like 1)
Description:
Is a negative regulator of proteasomal degradation of a set of methylated proteins, including DNMT1 and SOX2. Involved in the maintainance of embryonic stem cells pluripotency, through the regulation of SOX2 levels (By similarity).
Synonyms: CGI-72; FLJ13649; MGC64923; FLJ21615; TDRD20B; URLC1
Tractability: Small molecule: a structure with a bound ligand is known. Antibody: the Human Protein Atlas places it where antibodies can reach. PROTAC: UniProt records ubiquitination sites on it; ubiquitination databases record sites on it; its protein half-life has been measured.
Gene: Protein-coding gene on chromosome 8 (132,775,311 to 132,848,807, forward strand). Ensembl gene ENSG00000129292.
Subcellular location: Nucleus
Subcellular location (Human Protein Atlas): Nucleoplasm; Plasma membrane
Pathways (Reactome):
Gene expression (Transcription): Formation of WDR5-containing histone-modifying complexes
Gene Ontology:
Molecular function: methylation-dependent protein binding; protein binding
Biological process: negative regulation of proteasomal ubiquitin-dependent protein catabolic process; negative regulation of protein catabolic process; regulation of transcription by RNA polymerase II
Cellular component: nucleus; NSL complex; nucleoplasm
Genetic constraint (gnomAD): Loss-of-function variants: 15 observed, 35.83 expected, observed/expected ratio (o/e) 0.42, 90% interval 0.28 to 0.64. The upper end of that interval is the gene's LOEUF score, 0.64, which puts it in group 2 of 6, group 1 being the genes least tolerant of losing a copy. Missense variants: 455 observed, 505.44 expected, observed/expected ratio (o/e) 0.9, 90% interval 0.83 to 0.97. Synonymous variants: 150 observed, 173.95 expected, observed/expected ratio (o/e) 0.86, 90% interval 0.75 to 0.99.
Homologues: Orthologues: macaque PHF20L1 (99% identical), chimpanzee PHF20L1 (98% identical), dog PHF20L1 (95% identical), rabbit PHF20L1 (94% identical), pig PHF20L1 (93% identical), guinea pig PHF20L1 (91% identical), rat Phf20l1 (88% identical), mouse Phf20l1 (85% identical), tropical clawed frog phf20l1 (59% identical), zebrafish phf20l1 (50% identical), Drosophila melanogaster MBD-R2 (18% identical). Paralogues in human: PHF20 (33% identical).
Diseases named in the same sentence as PHF20L1 in open-access papers:
PHF20L1 is named in the same sentence as 14 diseases in open-access papers, as found by Europe PMC text mining. Sharing a sentence is not in itself a finding about the gene and the disease. The quoted sentences say what the papers report.
breast carcinoma (7 papers, 2012 to 2025). "Studies carried out in breast cancer demonstrated an increase in PHF20L1 expression associated with a poor prognosis." (PMID 34991589, 2022). "Amplification and overexpression of PHF20L1 were more significant in aggressive basal-like and Luminal B subtypes of breast cancer." (PMID 40723918, 2025). "In breast cancer, the expression of PHF20L1 was elevated and positively correlated with histological grading." (PMID 40723918, 2025). "The methylation level of the PHF20L1 promoter region is positively correlated with breast cancer metastasis." (PMID 40723918, 2025). "Aberrations in the PHF20L1 gene are highly correlated with various cancers, such as ovarian and breast cancer." (PMID 35033534, 2022). "As a H3K27me2 reader, PHD Finger Protein 20 Like 1(PHF20L1) plays important roles in promoting the Warburg effect via many glycolysis-related genes (GRGs) in breast cancer." (PMID 35004688, 2021). "We found that three PHFs (PYGO2, KDM5B, and PHF20L1) were overexpressed at the mRNA level (Z-score > 1) in more than 40% of breast cancers." (PMID 28055972, 2017). "We recently demonstrated that knockdown of PHF20L1 inhibits cell proliferation in breast cancer cell lines." (PMID 28055972, 2017). "Breast Cancer: The role of PHF20L1 in mouse development has been studied extensively." (PMID 40723918, 2025). "These miRNAs may play a significant role in the expression changes in PHF20L1, thereby promoting its role in breast cancer metastasis." (PMID 40723918, 2025). "A comprehensive analysis integrating copy number variations, gene expression, clinicopathological features, and patient survival data for 41 TDRD genes in breast cancer revealed that PHF20L1 was the most prominently amplified TDRD gene in TCGA breast cancer samples." (PMID 40723918, 2025). "For example, in breast cancer, depletion of PHF20L1 suppresses cancer growth." (PMID 35033534, 2022). "PHF20L1 is amplified and overexpressed in a subset of basal-like and Luminal B breast cancers." (PMID 28055972, 2017). "Notably, PHF20L1 was highly amplified in several cancers, including ovarian serous cystadenocarcinoma, breast cancer, liver cancer, and pancreatic adenocarcinoma, suggesting that it may play a critical role in tumourigenesis." (PMID 40723918, 2025). "In breast cancer, the expression of PHF20L1 may be regulated by microRNAs." (PMID 40723918, 2025). "In this study, we identified four PHFs, PYGO2, KDM5B, PHF20L1, and ASH1L, which were most commonly amplified/overexpressed in breast cancer." (PMID 28055972, 2017). "Studies have assessed the expression of this protein in breast cancer tissues, but no study has assessed PHF20L1 expression in EOC prior to ours." (PMID 34991589, 2022). "We speculate that PHF20L1 likely functions as a critical tethering factor, via its PHD and Tudor domains, to regulate DNA and histone methylation signals in breast cancer." (PMID 28055972, 2017). "For example, PHF20L1, BCAS3, TAOK1, PCGF2, and TRPS1 are fused in other breast cancers." (PMID 23260012, 2012).
breast tumor (2 papers, 2023 to 2024). "PHD Finger Protein 20-Like Protein 1 (PHF20L1) was reported as an H3K27me2 reader in the context of breast tumor growth, working with PRC2 and nucleosome remodeling and deacetylase (NuRD) complexes to facilitate transcriptional repression." (PMID 38076966, 2023).
ovarian carcinoma (2 papers, 2022 to 2025). A malignant neoplasm originating from the surface ovarian epithelium. "Immunohistochemical findings indicated that PHF20L1 was overexpressed in tumour tissue sections obtained from patients with ovarian cancer, and elevated PHF20L1 expression was associated with reduced progression-free and overall survival." (PMID 40723918, 2025). "Nevertheless, based on our results, we strongly suggest an association between the overexpression of PHF20L1 and poor prognosis in ovarian cancer patients." (PMID 34991589, 2022). "The results suggest that PHF20L1 could play a relevant role in ovarian cancer given that higher PHF20L1 protein expression is associated with lower overall patient survival." (PMID 34991589, 2022). "We previously reported that PHF20L1 is expressed as a fucosylated protein in SKOV-3 cells stimulated with ascites from patients with ovarian cancer." (PMID 34991589, 2022). "Immunohistochemical results suggest that PHF20L1 exhibits increased expression in sections of tumor tissues from patients with ovarian cancer and that higher PHF20L1 expression correlates with shorter progression-free survival and shorter overall survival." (PMID 34991589, 2022). "In ovarian cancer, alterations in the gene copy number of PHF20L1 were previously found by another research group." (PMID 34991589, 2022). "We demonstrated that the PHF20L1 protein is overexpressed in tumor tissues of patients with different ovarian cancer histotypes and that the level of expression increases as the disease progresses." (PMID 34991589, 2022). "SKOV-3 cell cultures were treated with ten different ascites fluid samples from epithelial ovarian cancer patients to evaluate their effect on PHF20L1 protein expression in the cell line by taking into account the heterogeneity of ascites." (PMID 34991589, 2022). "The results showed increased PHF20L1 expression in ovarian cancer tissue compared with healthy ovaries; overexpression showed a negative trend with patient progression-free survival (PFS) and overall survival (OS)." (PMID 34991589, 2022). "Given that ascites can modulate protein expression and, thereby, the cellular phenotype in ovarian cancer cells, the expression of PHF20L1 isoforms was analyzed to determine whether this ovarian cancer microenvironment could modulate their expression." (PMID 34991589, 2022). "Thus, in the present work, we focus on the relevance of PHF20L1 expression in tumor tissue sections and ovarian cancer cell lines and the correlations between its expression level and the clinical data of ovarian cancer patients." (PMID 34991589, 2022). "We decided to analyze the expression of PHF20L1 in ovarian cancer tissues, determine whether a correlation exists between PHF20L1 expression and patient clinical data, and analyze whether ascites can modulate the different isoforms of this protein." (PMID 34991589, 2022). "In this work, PHF20L1 protein was analyzed because it was previously identified as a fucosylated protein in ovarian cancer cell lines with an aggressive phenotype to evaluate its potential as a key component in the pathogenesis and/or as a possible biomarker of ovarian cancer." (PMID 34991589, 2022). "PHF20L1 is expressed as a fucosylated protein in ovarian cancer tissues and its expression increases in SKOV-3 cells stimulated by ascites in patients with ovarian cancer." (PMID 40723918, 2025). "The interaction of SOX-2 with PHF20L1 has already been demonstrated by others; SOX-2 and PHF8, another PHD finger protein, have been analyzed in ovarian cancer tumor tissues, showing that SOX-2 was overexpressed in mucinous carcinoma." (PMID 34991589, 2022). "PHD finger protein 20-like protein 1 (PHF20L1) is a transcriptional regulator with several isoforms, and studies on its role in ovarian cancer are limited." (PMID 34991589, 2022).
ovarian carcinoma (continued). "However, in tumor tissue, where we also observed high expression of PHF20L1, its regulation could be associated with both TGF-β, which is overexpressed in ovarian cancer tumor tissue, and with other components given that signaling via WNT or receptor tyrosine kinase would make more sense." (PMID 34991589, 2022). "We previously demonstrated the overexpression of PHF20L1 in tumor tissue; however, we do not know the functional role of this protein in ovarian cancer cells." (PMID 34991589, 2022).
brain tumor (1 paper, 2010). "Good agreement was also observed on alignment with the malignant brain tumor repeat (MBT) domain of PHF20L1 (PDB 2jtf) and the metal response element-binding transcription factor 2 (PDB 2eqj)." (PMID 21072162, 2010).
colorectal cancer (1 paper, 2025). A primary or metastatic malignant neoplasm that affects the colon or rectum. "Recent studies have demonstrated that in addition to its physiological roles during normal development, PHF20L1 is aberrantly overexpressed in several malignancies, including breast, ovarian, and colorectal cancers." (PMID 40723918, 2025). "Colorectal Cancer: The TCGA database showed that PHF20L1 is highly expressed in colorectal cancer tissues and is closely related to tumour growth and progression." (PMID 40723918, 2025). "This review comprehensively summarises the role of PHF20L1 in various cancers, including breast, ovarian, and colorectal cancers, as well as retinoblastomas, and elucidates its molecular mechanisms of action in cancer pathogenesis." (PMID 40723918, 2025). "In recent years, research on PHF20L1 has focused mainly on various malignant tumours, including breast, ovarian, and colorectal cancers, which accelerate the malignant development of cancer by promoting tumour cell proliferation, metastasis, and immune evasion." (PMID 40723918, 2025). "PHF20L1 inhibits the expression of HIC1, indirectly promoting the expression of Paired Box Gene 2 (PAX2) and driving malignant progression of colorectal cancer cells." (PMID 40723918, 2025). "PHF20L1 promotes EMT of colorectal cancer cells and increases their invasiveness and metastatic abilities; it also regulates the expression of various angiogenic factors (such as ANGPT2, FGF1, PDGFA, and VEGFA) and promotes angiogenesis in colorectal cancer tissues." (PMID 40723918, 2025).
herpesvirus infection (1 paper, 2024). "This study raises important questions regarding the mechanism of H3K27me2-specific targeting to viral genomes, the contribution of epigenetic heterogeneity to herpesvirus infection, and the role of PHF20L1 in regulating the outcome of DNA virus infection." (PMID 38411116, 2024).
retinoblastoma (1 paper, 2025). A malignant tumor that originates in the nuclear layer of the retina. "Retinoblastoma: Interaction between PHF20L1 and monomethylated pRb is crucial for maintaining the integrity of the pRb-dependent G1-S checkpoint." (PMID 40723918, 2025).
tumor (7 papers, 2012 to 2025). "Based on these results, we conclude that PHF20L1 is a protein that can be modulated by ascites components and suggest that its function and expression are important in cancer progression given that its overexpression in tumor tissues was associated with a worse prognosis." (PMID 34991589, 2022). "Immunotherapy Combination Strategies: As a component of the NSL complex, PHF20L1 regulates immune responses in tumour microenvironment (TME) by coordinating histone acetylation, including HDAC-mediated chromatin remodelling." (PMID 40723918, 2025). "Accumulating evidence indicates that PHF20L1 is upregulated in these malignancies and drives tumour progression by promoting proliferation, metastasis, and immune evasion." (PMID 40723918, 2025). "PHF20L1 interacts with various epigenetic complexes and regulates the expression of tumour-related genes through histone modifications." (PMID 40723918, 2025). "Furthermore, PHF20L1 orchestrates tumour-related gene expression by interacting with key epigenetic complexes." (PMID 40723918, 2025). "Moreover, PHF20L1 promotes tumour metabolic reprogramming, such as the Warburg effect, and chemotherapeutic resistance by regulating the MYC/HIF-1α signalling axis." (PMID 40723918, 2025). "PHF20L1 also plays an important role in maintaining the stemness of tumour stem cells." (PMID 40723918, 2025). "MiR-96-5p, miR-9-5p, and miR-182-5p may target PHF20L1 directly or indirectly, regulate genes involved in selective splicing, and contribute to tumour occurrence, invasion, and metastasis." (PMID 40723918, 2025). "PHF20L1 expression in tumor tissue was determined according to the immunoreactive score." (PMID 34991589, 2022). "HOXB9 and PHF20L1 are members of gene families that are fused in other neoplasms." (PMID 23260012, 2012). "Moreover, PHF20L1 alterations not only affect its own function but may also affect interactions with other genes, further influencing tumour cell proliferation, apoptosis, invasion, and metastasis." (PMID 40723918, 2025). "Experiments have confirmed that knockdown of PHF20L1 or LSD1 in PA-1 cells and mouse ESCs leads to the loss of SOX2 protein stability and significantly impairs the self-renewal capacity of stem cells, which provides a new molecular basis for therapeutic strategies targeting SOX2-positive tumours." (PMID 40723918, 2025). "PHF20L1 enhances the Warburg effect by promoting the methylation and deacetylation of H3K27, thereby promoting tumour progression." (PMID 40723918, 2025). "The role of PHF20L1 in multiple cancers suggests that PHD inhibitors may inhibit the function of PHF20L1 by modulating the PHD fingers’ activity, thereby slowing tumour progression." (PMID 40723918, 2025). "PHF20L1 directly inhibits a series of tumour suppressor factors, including Forkhead Box Protein K2 (FOXK2) and Hypermethylated in Cancer 1 (HIC1), through its synergistic action with the PRC2 and NuRD complexes, thereby driving glycolysis and promoting tumour occurrence." (PMID 40723918, 2025). "Expression levels of PYGO2, KDM5B, PHF20L1, and ZMYND8 were also significantly higher in tumor samples compared to that in non-tumor breast tissue." (PMID 28055972, 2017).
cancer (6 papers, 2017 to 2025). A tumor composed of atypical neoplastic, often pleomorphic cells that invade other tissues. "This suggested that PHF20L1 plays an important role in the development and occurrence of these cancers." (PMID 40723918, 2025). "Future research should further investigate the molecular regulatory networks of PHF20L1 in different cancers and other human diseases and focus on developing specific small-molecule inhibitors to enable precision-targeted therapies." (PMID 40723918, 2025). "The oncogenic role of PHF20L1 in cancer and its epigenetic regulatory characteristics make it a potential therapeutic target, particularly for cancers with overexpression and poor prognosis." (PMID 40723918, 2025). "PHF20L1 has been confirmed to influence malignant tumours and is a promising biomarker for diagnosis and treatment." (PMID 40723918, 2025). "PHF20L1 is expressed in various tissue, both in normal physiological contexts and in pathological conditions, such as cancer." (PMID 40723918, 2025). "Given MOF’s role in the regulation of gene expression and chromatin structure, and its de-regulation in a wide variety of cancers, we reasoned that its interaction with pRb via PHF20L1 would be an important determinant of pRb-dependent growth control." (PMID 28841214, 2017). "Although the current research has mainly focused on the function of PHF20L1 in cancer, its pleiotropic effects may extend to other diseases or physiological processes." (PMID 40723918, 2025). "PHF20L1 is a protein with Tudor and PHD finger domains that plays a pivotal role in the epigenetic regulation of cancer progression and other diseases." (PMID 40723918, 2025). "A similar observation was made for deep CNAs in ERGs, namely BOP1 (four cancers), ATAD2 (four cancers), MECOM (three cancers), and PHF20L1 (three cancers)." (PMID 32963031, 2020). "Targeting PHF20L1 or its related pathways, such as combining DNMT1 and G9a/GLP inhibitors, may be an effective strategy to reverse chemotherapeutic resistance and enhance the effectiveness of cancer treatments." (PMID 40723918, 2025).
infection (2 papers, 2023 to 2024). The state of being infected such as from the introduction of a foreign agent such as serum, vaccine, antigenic substance or organism. "In line with the role of H3K27me2 in lytic gene repression, we could also detect co-localization of viral genomes with PHF20L1 during lytic infection." (PMID 38411116, 2024). "In line with a role for H3K27me2 in lytic gene repression, we could also detect co-localization of viral genomes with PHF20L1 during lytic infection." (PMID 38076966, 2023). "Given the identified role for PHF20L1 as a repressive H3K27me2 reader, its co-localization with HSV-1 genomes strengthens the evidence for a mechanism by which H3K27me2 represses lytic genes soon after infection of a fibroblast." (PMID 38076966, 2023).
PHF20L1 also shares sentences with these, for which no sentence is quoted: Luminal B (1 paper); mucinous carcinoma (1); thyroid carcinoma (1); uterine corpus endometrial carcinoma (1).